BRCA1 (BRCA1 DNA repair associated)
Diseases named in the same sentence as BRCA1 in open-access papers (continued):
Sharing a sentence is not in itself a finding about the gene and the disease.
breast cancer (continued). "A zwitterionic peptide self-assembled monolayer (SAM) support that serves as the low fouling substrate was used to construct a highly sensitive and selective label free electrochemical DNA hybridization biosensor for the breast cancer marker BRCA1." (PMID 36832253, 2023). "For women carrying BRCA1 and BRCA2 P/LP germline variants, the cumulative breast cancer risks to age 80 are estimated at 72% and 69%, respectively." (PMID 37628558, 2023). "Stratified by gene group, 46 (0.8%) had a BRCA1/2 PLPV identified through comprehensive BRCA1/2 analysis; 60 (1.0%) had a PLPV in any of seven high-risk breast cancer genes; and 136 (2.3%) had a PLPV in any of 19 genes associated with breast or ovarian cancer." (PMID 37535880, 2023). "We have tested PREDICT model in retrospective follow-up data from BRCA1/2 carrier patients from the Consortium of Investigators of Modifiers of BRCA1/2 (CIMBA) and the Breast Cancer Association Consortium (BCAC)." (PMID 37173335, 2023). "Breast cancer cells combined with BRCA1/2-mutant and PARPi treatment would lead to the accumulation of DSB and bring in synthetic lethality." (PMID 37476378, 2023). "To assess BRCA1 methylation in breast cancer patients, we included all patients enrolled in three neoadjuvant breast cancer studies (the EPITAX, DDP, and PETREMAC trials) from whom pretreatment tumor tissue and matched WBC DNA samples were available." (PMID 38053165, 2023). "Breast cancer (BC) tumorigenesis is driven by various genes, among which are such classical tumor suppressors as BRCA1 and BRCA2." (PMID 37628606, 2023). "According to The Breast Cancer Information Core (BIC), a catalog of BRCA1 and BRCA2 mutations identified worldwide, the most commonly identified BRCA1 mutations are 185delAG (16.5%), 5382insC (8.8%), and the C61G missense mutation (1.8%)." (PMID 36902416, 2023). "This was completed by Mary Claire-King and her colleagues, who published a linkage analysis of families with an early onset of breast cancer (BC) and identified the gene locus of BRCA1 (BReast CAncer 1) at 17q21." (PMID 36902416, 2023). "For missense variants in aggregate, rare missense variants in specific domains in BRCA1, ATM, CHEK2, and PALB2 were significantly associated with increased risk of certain breast cancer subtypes." (PMID 37790698, 2023). "Mutations in the DNA repair genes BRCA1 and BRCA2 are associated with a substantially increased lifetime risk of breast cancer, and mutations in BRCA1 are particularly associated with the development of TNBC." (PMID 37568617, 2023). "In carriers of mutations in the BRCA1 and BRCA2 genes, the risk of developing breast cancer increases to even 80%." (PMID 37108398, 2023). "Among the several miRNA–mRNA target interactions in TNBC and/or breast cancer in general, the cancer driver genes, such as BRCA1, ESR1, PTEN, and AKT1, were observed." (PMID 37685851, 2023). "Several large studies have shown increased rates of TIL-high tumours in BRCA1/2 carriers when compared with all WT BRCA breast cancer patients." (PMID 36831687, 2023). "Examples include the BRCA1 and BRCA2 genes, which are associated with an increased risk of breast cancer." (PMID 38384741, 2023). "This investigation shed light on BRCA1’s complex role in breast cancer, emphasizing the importance of identifying its tissue-specific effects to devise optimal prevention and treatment strategies." (PMID 37762577, 2023). "BRCA1 and BRCA2 had affected 3% and 5% of the study population, respectively, and were collectively altered in 6%, with co-occurrence of BRCA1/2 in 7 breast cancers." (PMID 38098088, 2023). "Different miRNA expression profiles have been identified in healthy women, women with sporadic breast cancer and women with BRCA-mut breast cancer, and, to some degree, between BRCA1-, BRCA2- and BRCAX-related tumours." (PMID 36831687, 2023). "BRCA1 and BRCA2 (BReast CAncer genes 1 and 2) are well-known tumor suppressor genes linked to breast cancer." (PMID 36831644, 2023).
breast cancer (continued). "The most predominant cancer marker for breast cancer identification as well as monitoring is cancer antigen 15-3; additional biomarkers that are related to breast cancer are CA 27.29, BRCA1, BRCA2 and (carcinoembryonic antigen) CEA." (PMID 36979610, 2023). "BRCA1 depletion in the HR-proficient breast cancer cell line HS578T significantly increased TRDMT1i sensitivity, showing that TRDMT1 indeed has a BRCA1-independent function that is critical for the survival of BRCA1-deficient cells." (PMID 37777505, 2023). "The most common genetic alterations were c.1310_1313 delAAGA in the BRCA2 gene and c.5030_5033 delCTAA in the BRCA1 gene, which were found in 4% of the breast cancer patients and 20% of the ovarian cancer patients." (PMID 37298642, 2023). "Pathogenic germline variants in the BRCA1 and BRCA2 genes are present in 3% of all breast cancer cases." (PMID 36112334, 2023). "Two CNV-positive samples harbored BRCA1 exon 1-2 deletion, which has been reported to be recurrent in Chinese patients with breast cancer." (PMID 38274092, 2023). "The trapping of PARP at the site requires the recruitment of HR pathway machinery, which is defective in BRCA1/2-mutant breast cancer tumors." (PMID 35976445, 2023). "P/LP variants in BRCA1 confer a higher risk for breast cancer compared to P/LP variants in BRCA2 and RRM in women with asymptomatic BRCA1 P/LP variants has been shown to have improved survival compared to those who opted for IBS." (PMID 36971799, 2023). "55%–65% of BRCA1 mutation‐containing females and 45% of BRCA2 mutation‐containing females have a probability of developing breast cancer after the age of 70 years." (PMID 36971312, 2023). "The ATM gene is located on chromosome 11q22-23 and is one of the most common breast cancer (BC) vulnerability genes after BRCA1/2." (PMID 38021491, 2023). "A matched case-control study included 1665 pairs of women with BRCA1 (n = 1243 pairs) and BRCA2 (n = 422 pairs) P/LP germline variants to assess the association between breastfeeding and breast cancer risk." (PMID 37628558, 2023). "We previously reported the distribution and frequency of germline BRCA1 and BRCA2 variants in high-risk Jordanian breast cancer patients, chosen in accordance with international guidelines." (PMID 37920853, 2023). "In this study, we successfully knocked-in the BRCA1 E255* and the BRCA2 C711* mutations into the Capan-2 and T3M4 PDAC cell lines and in the MCF7 breast cancer cell-line, using CRISPR/Cas9-mediated technology." (PMID 37907567, 2023). "Germline pathogenic variants in the BRCA1 and BRCA2 genes are associated with high risks of developing breast cancer." (PMID 37444426, 2023). "Studies in breast cancer have shown that COH29 induces greater DSBs and DNA-damage response in BRCA1-deficient cells than in normal cells." (PMID 38124207, 2023). "Of the 79 women with a personal history of breast cancer, 52 (65.8%) had P/LP variants in BRCA2 gene, while 27 (34.2%) had P/LP variants in BRCA1 gene." (PMID 36971799, 2023). "The tumor suppressor gene BRCA1 related with breast cancer in women is also involved in the pathogenesis of AD due to its accumulation in the brain." (PMID 36778155, 2023). "Notably, not only BRCA1/2 but also many other genes can harbor predisposing genetic variants that contribute to breast cancer (BC) susceptibility." (PMID 38003901, 2023). "In the American Cancer Society’s study of newly diagnosed breast cancer, 10% of patients had breast cancer gene 1 (BRCA1) and breast cancer gene 2 (BRCA2) mutations, whereas 35% of patients with TNBC carried a BRCA1 mutation, and 8% carried a BRCA2 mutation." (PMID 37513983, 2023).
breast cancer (continued). "Recently, research showed that PARP inhibitors inhibit the BRCA1/2-intact breast cancer cell growth through ribosome biogenesis and rDNA transcription." (PMID 37564214, 2023). "To that end, we assessed miR-155-5p expression in the highly BRCA1-methylated breast cancer cells HCC-38 and UACC-3199." (PMID 37240365, 2023). "Patients with germline BRCA1 and/or BRCA2 pathogenic variants and HER2-negative, high-risk early breast cancer who had received neoadjuvant or adjuvant chemotherapy and completed local treatment were eligible." (PMID 37005966, 2023). "Breast cancer 1/2 gene (BRCA1/2) and others involved in homologous recombination repair (HRR) gene mutation or function can cause homologous recombination deficiency (HRD), causing malignant transformation in cells." (PMID 37426808, 2023). "It is estimated that 40%-80% of carriers of BRCA1 and BRCA2 mutations have a probability of developing breast cancer and increased risk is also associated with family history." (PMID 37719058, 2023). "We illustrate the use of this method to calculate LRs for 24 BRCA1 and 68 BRCA2 variants from breast cancer case-control genotype data generated by the Breast Cancer Association Consortium (BCAC) as part of the large-scale OncoArray project." (PMID 38725546, 2023). "BRCA1 and BRCA2 mutations are found in around 10% of IBC diagnoses and confer a 5–10-fold increase in the odds of developing breast cancer." (PMID 37686673, 2023). "Gestational resveratrol supplementation was demonstrated to induce breast cancer-1 promoter (BRCA-1) hypermethylation and to decrease BRCA-1 expression in the mammary tissue of rat offspring." (PMID 36829900, 2023). "Mutations in the tumor suppressor genes BRCA1 and BRCA2 are responsible for the majority of hereditary breast cancer cases." (PMID 37138170, 2023). "(LCS=291) investigated the efficacy and safety of Olaparib in germline BRCA1/2 (gBRCA1/2)-mutant breast cancer." (PMID 37476378, 2023). "The disruption of the function of the BRCA1 tumor suppressor plays a key role in the development of many breast cancers." (PMID 37627161, 2023). "Explore the efficacy and safety of PARPi drugs like Olaparib and Talazoparib in BRCA1/2-mutant breast cancer." (PMID 37476378, 2023). "Three of these genes are related to the DNA Interstrand Crosslink Repair: BRCA1 and BRCA2 are the quintessential breast cancer susceptibility genes." (PMID 37182128, 2023). "Similar to in women, mutations in the BRCA1 and BRCA2 genes have been linked to a four-fold increased risk of mammary tumor development in dogs." (PMID 37368765, 2023). "Mutations of BRCA1 and BRCA2 genes significantly impact the DNA repair system, accounting for approximately 2–3% of breast cancer events and over 10% in TNBC." (PMID 37237509, 2023). "Since the discovery of the high-risk breast cancer predisposition genes BRCA1 and BRCA2, extensive efforts have tried to identify additional breast cancer predisposition genes." (PMID 36707629, 2023). "While in the treatment of BRCA1/2-mutant breast cancer, it continues to involve highly invasive surgical procedures like most cancers." (PMID 37476378, 2023). "In the case of breast cancer, 10-15% of women with sporadic tumors exhibit BRCA1 TSG hypermethylation, accompanied by an expression pattern consistent with hereditary tumors." (PMID 37564937, 2023).
breast cancer (continued). "The most common marker genes for the development of breast cancer are BRCA1 and BRCA2, which have fundamental functions in the repair of homologous DNA (deoxyribonucleic acid)." (PMID 38156855, 2023). "Two recent large studies demonstrated that CHEK2 is the second most frequently altered breast cancer predisposition gene among patients of European descent, surpassed by BRCA2 and followed by BRCA1 in frequency of germline pathogenic variants." (PMID 37449874, 2023). "Among genetic factors, germline pathogenic variants/likely pathogenic variants (PVs/LPVs) in the BRCA1 and BRCA2 genes account for a large proportion of hereditary breast cancer cases worldwide." (PMID 38017116, 2023). "In another work, a highly sensitive electrochemical genosensor was developed using a RGO-yttria nanocomposite (rGO:Y) as the immobilization platform for detecting the breast-cancer-related BRCA1 gene." (PMID 37764496, 2023). "Extending these findings to a human system, the survival of Polθ- and BRCA1-co-depleted CAL51 human basal breast cancer epithelial cells was improved by low-concentration RAD52 inhibitor or treatment with a low concentration of RAD52 siRNA." (PMID 38030626, 2023). "(LCS=357) indicated that breast cancer and contralateral breast cancer are more likely for BRCA1 and BRCA2 carriers through a prospective study." (PMID 37476378, 2023). "The notion that ER+ breast cancer in BRCA2 carriers has special prognostic properties is supported by findings of increased rate of high recurrence scores (RS) in BRCA1/2 carriers." (PMID 38036573, 2023). "reviewed 9 studies reported on the incidence of primary breast cancer following NSM in BRCA1/2 unaffected carriers who undergo prophylactic bilateral mastectomy." (PMID 37781190, 2023). "On the other hand, RBBP8 functions as a tumor suppressor protein in breast cancer by interacting with some distinct tumor-suppressing factors, including BRCA1 and retinoblastoma." (PMID 36960071, 2023). "BRCA1 and BRCA2 (known as BReast CAncer genes 1 and 2) are the most widely recognized breast cancer susceptibility genes." (PMID 37958392, 2023). "A retrospective cohort study in North America and Western Europe investigated families with ovarian or breast cancer and found the relative risk of CRC in BRCA1 mutation carriers to be 4.11 (95% CI, 2.36–7.15)." (PMID 37644384, 2023). "Highly methylated in BRCA-1related breast cancers, Fox A1’s methylation possibly stems from BRCA-1 gene control over Fox A1 expression via methyltransferase inhibition." (PMID 37746260, 2023). "ZNF350, a transcriptional suppressor, binds to BRCA1 and CtIP to form a transcriptional suppressor complex that inhibits angiogenesis in breast cancer." (PMID 38049396, 2023). "In conclusion, our research sheds new light on the regulatory pathways in BRCA1 mutant breast cancer." (PMID 36614323, 2023). "Variants in key genes of HR, such as BRCA1, BRCA2, PALB2, BARD1, RAD51C, and RAD51D, which alter their function and/or their expression, have a significant association with breast cancer risk." (PMID 37372450, 2023). "In our study breast cancer was the most common cancer among female relatives of both BRCA1 and BRCA2 carriers." (PMID 36861435, 2023). "The risk of breast cancer increases with the number of first and second-degree relatives diagnosed with BRCA1 and breast cancer." (PMID 37476378, 2023).
breast cancer (continued). "Here, we demonstrate, for the first time, that SOC therapies used in ER+ breast cancer induce DNA damage, and toxic PARP1 trapping upon generation of a functional BRCAness phenotype through loss of key DNA repair proteins, including BRCA1, BRCA2 and RAD51." (PMID 37914699, 2023). "In terms of IHC phenotypes, 13 (2.3%) of the BRCA1 mutant breast cancers were HR+/HER2−, 3 (3.3%) were HR+/HER2+, 2 (2.6%) were HR−/HER2+, and 9 (6.9%) were HR−/HER2−." (PMID 38098088, 2023). "P/LP variants in cancer-predisposing genes like BRCA1 and BRCA2 account for 5%–10% of breast cancer cases." (PMID 37920853, 2023). "Breast cancer genes 1 and 2 (BRCA1, BRCA2) are two tumor suppressor genes that strongly impact a women’s overall risk of developing breast and ovarian cancer." (PMID 37228496, 2023). "The cumulative risk of breast cancer in carriers of variants in BRCA1 and BRCA2 genes was reported to be 72% and 69%, respectively, and women with BRCA1/2 variants are advised to undergo prophylactic risk-reducing surgery to decrease cancer-related mortality." (PMID 37656691, 2023). "The prevalence of the BRCA1 and BRCA2 mutations among Asian Americans with strong personal and/or family history of breast cancer was about 11.5% and 13%, respectively." (PMID 36834079, 2023). "Multiple other studies had confirmed the high rate of IBTR in BRCA1/2 carriers treated with BCS compared to matched controls with sporadic breast cancer." (PMID 37781190, 2023). "In the present study we aimed to clarify and characterize the spectra and risks of cancers in relatives of BRCA1/2 carriers in a large series of unselected Chinese patients with breast cancer." (PMID 36861435, 2023). "The lifetime risk of PDAC is about 1% for BRCA1 and 4.9% for BRCA2 PV/LPVs carriers, and studies by the Breast Cancer Linkage Consortium reported a 2.3-fold and 3.5-fold increased risk of PDAC in carriers of BRCA1- and BRCA2-altered variants, respectively." (PMID 37046793, 2023). "Distribution of VUS in breast cancer predisposing genes were :APC:1(5.8%), ATM:2(11.7%), BRCA1:1(5.8%), BRCA2:5(29.4%), BRIP1:1(5.8%), CDKN2A:1(5.8%), CHEK2:2(11.7%), FANC1:1(5.8%), MET:1(5.8%), STK11:1(5.8%), NF2:1(5.8%)." (PMID 37277882, 2023). "The Talazoparib Beyond BRCA (TBB) trial included any solid tumor with germline or somatic mutations in HR-related genes other than BRCA1 and BRCA2 in cohort B. They reported a 31% overall response rate in breast cancer patients." (PMID 38098088, 2023). "Expanding on this, the study examined the consequences of BRCA1 knockdown in ERα+ luminal breast cancer cells." (PMID 37762577, 2023). "Another study examined the interplay between BRCA1 and hypoxia in the context of cancer cell stemness using breast cancer cell lines." (PMID 37762577, 2023). "Breast Cancer 1 (BRCA1) and Breast Cancer 2 (BRCA2) pathways are observed in over 18% of women with High-Grade Serous Ovarian Cancer (HGSOC)." (PMID 37511995, 2023). "These include mutations in the breast cancer type 1 and 2 susceptibility gene (BRCA1 and BRCA2); a mutation in one of these genes is associated with a 55–70% probability of developing breast cancer." (PMID 37108425, 2023). "Two components of the FA signaling pathway, namely BRCA1 and BRCA2, function as susceptibility genes for breast cancer." (PMID 38025539, 2023). "Women with pathogenic variants in BRCA1 and BRCA2 genes are considered a high-risk category for breast cancer having a lifetime risk of developing a breast malignancy of 85% and 40–45%, respectively." (PMID 38017478, 2023). "Of the limited descriptive studies to date in familial breast cancer, when compared with sporadic tumours, there is a markedly reduced frequency of somatic PIK3CA mutations in BRCA1/2mut tumours (5–16%)." (PMID 36831687, 2023).